EGFR (epidermal growth factor receptor)
Diseases named in the same sentence as EGFR in open-access papers (continued):
Sharing a sentence is not in itself a finding about the gene and the disease.
glioma (continued). "For example, BMP4 treatment only is effective in sensitizing those glioma stem cells with high EGFR expression to TMZ treatment, leading to the accumulation of FOXO3a in the nucleus." (PMID 37821870, 2023). "measured pre-diagnostic serum levels of EGFR and human epidermal growth factor receptor 2 (HER2) in glioma patients." (PMID 37265788, 2023). "These in silico studies led to the discovery of 18 candidate inhibitors for EGFR, 6 for PI3Kp110β, and 3 dual inhibitors of both targets, which efficacy against glioma cells was validated in parental and EGFR overexpressing cell lines." (PMID 37568789, 2023). "In particular, EGFR (22/26) and CDK4 (6/8) mutations were more present in patients with GBM than those with other gliomas, whereas PDGFRA CNVs were present only in patients with GBM (3/3; data not shown)." (PMID 36959606, 2023). "High-grade gliomas exhibit inactivation of p16INK4a/p19ARF and activation of epidermal growth factor receptor (EGFR)." (PMID 36229714, 2023). "EGFR gene amplification is detected in 57.4% patients presenting primary GBM specific to the classical subtype of glioma." (PMID 37446288, 2023). "It has been described to interact with common signaling pathways involved in glioma pathogenesis, as focal adhesion kinase, epidermal growth factor receptor, and NFκB." (PMID 37296870, 2023). "Although IFN-γ has been reported to lead to increased EGFR activity in other cancer types, it is notable that this relationship persists in glioma, a CNS tumor with an immune microenvironment completely different from that of peripheral solid tumors." (PMID 37759950, 2023). "As a transcriptional co-activator of STAT3, TRIM24 leads to the activation of STAT3 downstream signaling in response to EGFR in glioma cells, ultimately supporting the stem cell-like phenotype." (PMID 36674511, 2023). "This research aimed to explore the relationship between IFN-gamma and EGFR in the context of gliomas, followed by an investigation of their effects on the TME." (PMID 37759950, 2023). "Their failure was unexpected considering the prevalence of EGFR amplification in glioma, and the most significant factor contributing to this failure was inadequate target inhibition and drug resistance." (PMID 37408388, 2023). "GliomaSCAN is a big NGS panel comprising 232 genes for detecting most of the glioma markers, including SNPs, CNVs (1p/19q-codeletion and chr +7/-10), and amplifications (EGFR, PDGFRA)." (PMID 37908227, 2023). "In contrast, TRIM24 activates the WNT pathway and other signaling pathways in gliomas, such as the EGFR and STAT3 pathways." (PMID 37686489, 2023). "Adult gliomas often exhibit genetic alterations such as mutations in the IDH1/2 genes, EGFR amplification, and loss of chromosome 10q." (PMID 37444408, 2023). "Overall, this aligns with previously reported findings on the significance of EGFR, situated on chromosomal region 7p11.2, in glioma function." (PMID 38067243, 2023). "latifolia was shown to target epidermal growth factor receptor (EGFR) signaling in the glioma cell lines LN229 and U251, as indicated in a network pharmacology analysis." (PMID 37568716, 2023). "Compared to glioses, glial neoplasms were significantly more often positive (p < 0.001, χ2) for EGFR (33.8%), MEOX2 (48.9%), SOX11 (69.9%) and INSM1 (64.9%)." (PMID 37568909, 2023). "Extensive genetic studies need to be conducted to confirm or refute the impact of EGFR, while it is important to note that gliomas demonstrate various molecular characteristics." (PMID 38067243, 2023). "Amplification of epidermal growth factor receptor (EGFR) was observed in about 50% of glioma patients, making anti-EGFR therapy a possible choice for glioma patients." (PMID 37444531, 2023). "Taken together, these results indicated that β-sitosterol significantly downregulated the EGFR/MAPK pathway in glioma cells." (PMID 38143380, 2023). "Thus, glioma cases with mutations in the EGFR kinase domain may benefit from EGFR TKIs." (PMID 35695190, 2023).
glioma (continued). "This revealed that RNF8low gliomas expressed significantly higher levels of HER2-pY1248 and EGFR-pY1173 than RNF8high gliomas, consistent with the role of receptor tyrosine kinase signaling being a core regulatory circuitry in gliomagenesis." (PMID 37468549, 2023). "A substantial percentage of gliomas present other alterations that can lead to a gain of 7q that contains the EGFR gene." (PMID 37446288, 2023). "CD44-HA mediated cell invasion can be modulated by EGFR, a well-known receptor overexpressed in gliomas." (PMID 36980765, 2023). "Specifically, lower mean ADC and the lower 5th percentile of ADC values were potentially useful imaging biomarkers for EGFR amplification in IDH‐wild‐type glioma." (PMID 36866773, 2023). "Most glioma tumors are dependent on EGFR signaling, making approved drugs targeting this gene attractive for precision oncology of gliomas." (PMID 38264526, 2023). "Overall, there are five major types of EGFR large fragment deletion across the EGFR extracellular region and carboxyl‐terminal (C‐terminal) domain which were originally discovered in gliomas." (PMID 36622089, 2023). "EphrinA5 was described to act as a tumor suppressor in glioma by negatively regulating the epidermal growth factor receptor (EGFR)." (PMID 37880732, 2023). "The epidermal growth factor receptor (EGFR) gene is one of the frequently altered loci in gliomas, leading to the activation of the EGFR signaling pathway and thus, promoting the genesis of gliomas." (PMID 37759950, 2023). "In a phase 1 study (NCT01800695), 1.25 mg/kg intravenous depatux-M every two weeks was well tolerated in 66 EGFR-amplified recurrent-glioma patients." (PMID 37444531, 2023). "NSCs of the SEZ are considered glioma cells of origin, and molecular alterations of the EGFR/PI3K/AKT/mTOR module are hallmarks of this cancer type, which has led to the design of clinical trials devised to target this pathway." (PMID 37542079, 2023). "Intracerebral injection of this boron entity in rats bearing EGFR overexpressing gliomas led to the tumor-specific accumulation of the boron dendrimers." (PMID 37408232, 2023). "Constitutively activated STAT3 is frequently co-expressed with EGFR in high-grade gliomas and cooperates with EGFR to facilitate epithelial-mesenchymal transition in human epithelial cancers." (PMID 36979412, 2023). "Researchers have investigated the effects of cancer stem signaling on differentiated glioma cells using U87MG models that harbor oncogene EGFR‐VIII." (PMID 36602390, 2023). "EGFR expression and cell proliferation were not affected by glutamate when cells were exposed to DNQX, an AMPAR inhibitor, which suggests that EGFR expression downstream from AMPAR activation contributes to glioma progression." (PMID 36614191, 2023). "In total, 1027 glioma samples were divided into four groups based on EGFR and IFN-γ related signatures." (PMID 37759950, 2023). "Gliomas increase EGFR via overexpression of the gene or its amplification on chromosome 7p12 or the formation of a truncating mutation that produces constitutively active EGFRvIII." (PMID 38067243, 2023). "ADC values were also successfully used in a multi‐center study to predict the EGFR amplification status of IDH‐wild‐type WHO grade II‐III gliomas." (PMID 36866773, 2023). "Glioma with higher PVT1 expression was significantly associated with the somatic mutation of PTEN, EGFR and TTN." (PMID 37202742, 2023). "In glioma cells, NF2 is phosphorylated and inactivated, which upregulates YAP1 expression and mediates the activation of epidermal growth factor receptor and Notch signalling pathways, promoting glioma cell proliferation and tumour formation." (PMID 37423952, 2023).
glioma (continued). "PLCG1, a member of the phospholipase C (PLC) family of enzymes, is involved in the development of glioma through the activation of growth factors such as EGFR and PDGFR." (PMID 38025749, 2023). "Signaling pathways such as the MAPK, PI3K, focal adhesion‐PI3K/AKT/mTOR, and EGFR pathways were enriched in gliomas with high MAPK4 expression." (PMID 36999945, 2023). "GSEA also showed that signaling pathways (MAPK, PI3K, Focal_adhesion‐PI3K/AKT/mTOR and EGFR) were significantly enriched in gliomas with high MAPK4 expression." (PMID 36999945, 2023). "For instance, glioma cells with mutant EGFR express IL‐6 and/or LIF cytokines, which can activate amplified wild‐type EGFR in neighboring cells, resulting in enhanced proliferation." (PMID 37492150, 2023). "A recent study evaluated the potential use of 89Zr-DFO-nimotuzumab in assessing the EGFR status in glioma." (PMID 39355049, 2023). "It has been found that EGFR-induced changes in the TME can in turn increase the malignant phenotype or drug resistance of glioma cells, which further illustrates the potential therapeutic benefit of targeting EGFR." (PMID 37759950, 2023). "The amount of circRNA changes with environmental conditions, for example, circ-EGFR in gliomas, especially oncogenes and drug resistance genes, and the amount of circRNA changes dynamically with different periods of division." (PMID 36895010, 2023). "Previous findings reported that co-deletion of p16INK4a/p19ARF in NSCs with constitutive EGFR activation induce the phenotype of high-grade glioma." (PMID 36229714, 2023). "Depatuxizumab mafodotin (ABT-414), an EGFR-targeting antibody–drug conjugate, selectively killed tumor cells overexpressing wild-type or mutant forms of EGFR and reduced glioma growth in mice." (PMID 36900355, 2023). "We postulated that immunohistochemical detection of proteins expressed preferentially in gliomas (EGFR, MEOX2, CD34) or during embryonal development (SOX11, INSM1) can be used to distinguish reactive gliosis from glioma." (PMID 37568909, 2023). "Primary genetic markers such as IDH mutations, CDKN2A deletions, 1p/19q‐codeletions, H3F3A alterations, MGMT promoter methylation status and EGFR amplification are used in the glioma classification system." (PMID 36999945, 2023). "The results showed that the mRNA expression level of EGFR was significantly decreased in IFI30‐silenced glioma cells but increased in IFI30‐overexpressing cells." (PMID 37408388, 2023). "Meanwhile, 62.5% (35/56) glioma specimen with high NFAT5 K668 methylation levels displayed enhanced protein expression of EGFR pY1068." (PMID 37429858, 2023). "For example, depatuxizumab mafodotin (ABT-414), an ADC targeting EGFR, has shown potential in the treatment of recurrent gliomas." (PMID 37629304, 2023). "The most intensely investigated targets for drug delivery to high-grade gliomas are vascular endothelial growth factor (VEGF) and epidermal growth factor receptor (EGFR), including the truncated, constitutively active variant EGFRvIII." (PMID 37513992, 2023). "In research, it was found that the epidermal growth factor receptor activation in the glioma is induced by COX-2 (cyclooxygenase 2-self-dependent prognostic factor in glioma) expression, through P38 mitogen activation of SP1/SP3." (PMID 37298889, 2023). "After the binding of extracellular ligands like reactive astrocytes and microglias secreted by glioma cells and tumor microenvironmental cells, EGFR suffers dimerization followed by trans-autophosphorylation of its intracellular domain." (PMID 37446288, 2023).
glioma (continued). "EGFR/Src signalling is often aberrantly upregulated in glioma, promoting cell proliferation and migration where it is associated with tumour progression and neoangiogenesis." (PMID 36932446, 2023). "In conclusion, this study provides novel insights into the relationship between IFN-γ-related and EGFR-related pathways in glioma patients." (PMID 37759950, 2023). "Astrocytes were identified as the causative cells of gliomas in the 1980s, and features such as mutated epidermal growth factor receptor (EGFR) and activation of H-RAS, considered representative signatures of gliomas, were revealed in a mouse model." (PMID 37723542, 2023). "It has been reported that the activation of the PI3K-AKT, Wnt, and EGFR pathways in glioma samples can all promote the upregulation of PD-L1 expression levels." (PMID 38022677, 2023). "The overexpression of epidermal growth factor receptor (EGFR) is known to enhance cell survival in epithelial cancers and gliomas." (PMID 38135951, 2023). "As EGFR is a prime target for gliomas and contribute to temozolomide resistance, the combination therapy can be a viable option for glioma treatment and induction of NK cell anti-tumor activity." (PMID 36792722, 2023). "The cytotoxicity and degranulation of the expanded NK cells were measured in vitro from co‐cultures with the glioma cell lines U‐87 MG, U‐87 MG EGFR vIII, LN-229, U-118 and DK-MG." (PMID 37841273, 2023). "This was then bound to the Fc component of Cetuximab, a humanized chimeric monoclonal antibody targeting the epidermal growth factor receptor (EGFR), in order to target F98 rat glioma tumor cells overexpressing EGFR." (PMID 37408232, 2023). "Currently, molecular markers for adult glioma classification and prognosis include IDH1/2 mutations, homozygous deletion of CDKN2A and/or CDKN2B, EGFR amplification, and TERT promoter mutation." (PMID 37214395, 2023). "Glial neoplasms were significantly more often (p < 0.001, χ2) positive for EGFR (34.1% vs. 0%), MEOX2 (49.3% vs. 2.3%), SOX11 (70.5% vs. 20.4%), and INSM1 (65.4% vs. 2.3%)." (PMID 37568909, 2023). "Epidermal growth factor receptor variant III (EGFRvIII, the deletion of exons 2–7) is a recurrent intragenic EGFR::EGFR.E1E8 fusion that occurs in high-grade gliomas." (PMID 38201434, 2023). "The current National Comprehensive Cancer Network (NCCN) guidelines for central nervous system cancers (Version 2.2022) recommend that first-line EGFR-TKIs alone should be considered in asymptomatic patients." (PMID 37904083, 2023). "We evaluated the applicability of this method by detecting the presence of IgG against a tumor-specific EGFR phospho-peptide in plasma from glioma patients." (PMID 35563452, 2022). "In contrast, the TERT and EGFR somatic mutations and CDKN2A/B copy number alterations are significantly depleted in the Chinese glioma cohort (P < 0.05)." (PMID 36350002, 2022). "The use of the PEG3400 linker created a spacer >200 atoms in length between the EGF and the biotin/SA complex and this extended linker removed the steric hindrance of the SA complex on EGF binding to the EGFR on human glial tumor cells." (PMID 35745855, 2022). "It has been reported that EGFR acts as the upstream signaling molecule of the AKT pathway in the suppression of inhibitor of differentiation 3 (ID3)-stimulated IL-8 expression in glioma stem-like cells." (PMID 35326180, 2022). "This work showed that GBP2 promoted proliferation and migration in glioma cells by regulating EGFR signaling pathway through interactions with KIF22." (PMID 35436989, 2022). "Immunohistochemistry (IHC) and immunofluorescence (IF) in fixed tissue samples of glioma patients were used to evaluate the expression and localization of EGFR, MMP9, and MUC4." (PMID 36400876, 2022). "Since 2021, EGFR has been included into the WHO classification of gliomas as a molecular genetic marker." (PMID 36615487, 2022).
glioma (continued). "Collectively, these studies show that EGFR is a critical factor in gliomas’ development and progression through its implication in the regulation of the proto-oncogene MYC family and the activation of the glutamine metabolism through the activation of ELK1." (PMID 35912242, 2022). "The present research suggests that IDH1 mutation, 1p19q LOH, EGFR mutation and MGMT promoter methylation are newly added major molecular markers for genetic molecular typing of glioma." (PMID 36181110, 2022). "EGFR (21%), PTEN (17%), and NF1 (12%) mutations in the high-glioma risk score group and CIC (28%), FUBP1 (11%), and NOTCH1 (10%) mutations in the low-risk score group were identified, and the mutation frequency of these genes was greater than 10%." (PMID 36311792, 2022). "The GISTIC 2.0 assessment uncovered numerous remarkable amplified regions containing multiple oncogenes in glioma patients with higher risk scores, consisting of 1q32.1 (PIK3C2B), 12q14·1(CDK4), 7p11·2 (EGFR), and 4q12 (PDGFRA)." (PMID 36311792, 2022). "This conjugate was selective and increased the accumulation of boron in F98 glioma cells (overexpressed EGFR) compared to normal mouse astrocytes." (PMID 36499115, 2022). "Gliomas can be induced in zebrafish by activation of the EGFR/RAS/ERK/AKT pathway via overexpression (a zic4 enhancer) of several oncogenes, such as KRASV12, EGFRvIII, among others." (PMID 35706426, 2022). "CHQ expresses its anticancer effect through the inhibition of autophagy or interference with PI3K/Akt or EGFR signaling pathways in glioma cells." (PMID 35954371, 2022). "The discovery of EGFR gene amplification in GBMs led to the development of a genetically engineered subline C6 glioma which expressed amplified human EGFR and was designated C-EGFR." (PMID 35446393, 2022). "In the microenvironment of glioma and in the tumor microenvironment, the EGFR and the IL6 signaling pathway play important roles in activating STAT3." (PMID 35783263, 2022). "The most common four shared pathways were: “Neurotrophin signaling pathway”, “Pancreatic cancer”, “Glioma”, “EGFR tyrosine kinase inhibitor resistance”." (PMID 35456446, 2022). "In a pilot study, the uptake of [O-methyl-11C]PD153035 was correlated to the EGFR expression levels (determined by immunohistochemistry and western blot) in gliomas." (PMID 35455447, 2022). "We stratified the adult gliomas into 6 molecular grades based on IDH mutations, 1p19q codeletion, TERTp mutation, BRAF mutation, EGFR amplification, 10q loss, and H3 mutations." (PMID 35558510, 2022). "Despite the failures in the treatment of gliomas with EGFR inhibitors, EGFR remains an attractive molecular target and marker of distinct biologic subtypes." (PMID 35628161, 2022). "The four-most-common shared pathways were: “Neurotrophin signaling pathway”, “Pancreatic cancer”, “Glioma”, “EGFR tyrosine kinase inhibitor resistance”." (PMID 35456446, 2022). "In glial tumors, where increased EGFR expression is a characteristic feature of primary tumors, miRNAs that control EGFR expression reflect corresponding abnormalities and tumor progression." (PMID 35330864, 2022). "We previously demonstrated the increased expressions of ER stress markers in U87Δ EGFR glioma cells treated with Ad-SGE-REIC." (PMID 36006934, 2022). "The detection and reporting of alterations such as IDH1/2 mutation, 1p/19q co-deletion, EGFR amplification, TERT-promoter mutation, and CDKN2A homozygous loss in the diagnosis of infiltrating glioma has become standard practice in clinical neuropathology." (PMID 36397144, 2022).